IL6 (interleukin 6)
Diseases named in the same sentence as IL6 in open-access papers (continued):
Sharing a sentence is not in itself a finding about the gene and the disease.
cervical carcinoma (continued). "Increased secretion of IL‐6 changes the regulation of cervical cancer cells on the secretion profile of macrophage cytokines and promotes the recruitment of macrophages in cervical cancer cell supernatants." (PMID 31943744, 2020). "Therefore, controversy and inconformity still remained about IL-12B rs3212227 and IL-6 rs1800795 polymorphisms and most of studies recruited a limited sample capacity, which is insufficient to get a firm conclusion about the associations of these polymorphisms with development of cervical cancer." (PMID 32458622, 2020). "The predominant pathogen of AV can decrease the beneficial effects of lactobacillus, causing inflammation, such as increased levels of IL-6, IL-8 and TNF-α, increasing the risk of HPV 16 infection which results in CIN or cervical cancer." (PMID 32605571, 2020). "STAT3-binding sequence in the enhancer region of lncRNA MALAT1 was demonstrated to be crucial for the IL-6- or STAT3-induced MALAT1 promoter activation in cervical cancer HeLa cells." (PMID 33274204, 2020). "There have been attempts to understand the mechanism of IL-6 in promoting cervical cancer development." (PMID 31470515, 2019). "We previously reported its effects against cervical cancer cells and continued to elucidate the effects of KP on inhibiting the production and secretion of interleukin (IL)-6, as well as its relevant signaling pathways involved in cervical tumorigenesis." (PMID 31470515, 2019). "Stromal fibroblasts induce CCL20 through IL6/C/EBPβ to support the recruitment of Th17 cells during cervical cancer progression." (PMID 31395078, 2019). "Recently, it has been clearly demonstrated that the autocrine and paracrine actions of IL-6 are essential for STAT3 activation in HPV18-positive cervical cancer cell lines (SW756 and HeLa)." (PMID 31470515, 2019). "Apart from both in vitro and in vivo data supporting a critical role of EGFR in MUC1-mediated paclitaxel-resistance, our clinical study showed elevated expression of MUC1, EGFR, and IL-6 in post-chemotherapy cervical cancer tissues." (PMID 31772161, 2019). "The PI3K/AKT signalling pathway is frequently activated in cervical cancers due to mutations in the PIK3CA gene, and AKT can activate NFκB and mediate IL-6 expression in some cancers." (PMID 31226168, 2019). "We noted increased IL-6 mRNA expression in high-grade cervical disease samples and in cervical cancer samples compared to healthy controls." (PMID 31226168, 2019). "IL-6 has been reported to be highly expressed in invasive cervical carcinoma and is associated with the pathogenesis of HPV-related cervical carcinoma." (PMID 31470515, 2019). "The increased phosphorylation of STAT3 in HPV positive cervical cancer cells was attributed to an increase in IL-6 expression by HPV E6 and the induction of autocrine/paracrine IL-6/gp130/STAT3 signalling." (PMID 31226168, 2019). "As with our analysis of CIN, IL-6 expression in the cervical cancer cases clearly separates into 2 subsets; IL-6 high (n = 7; 25.9%) and IL-6 low (n = 20; 74.1%)." (PMID 31226168, 2019). "Exosomal miR-155-5p derived from HIV-1-infected T cells promotes the malignant progression of cervical cancer by inducing the secretion of IL-1, IL-6 and IL-8." (PMID 31595161, 2019). "More importantly, positive correlations between the expressions of MUC1, EGFR, and IL-6 were found in 20 cervical cancer patients after chemotherapy." (PMID 31772161, 2019). "Recently, accumulated evidence has elucidated the roles of the inflammatory cytokine IL-6 in the pathogenesis of HPV-positive cervical cancers." (PMID 31470515, 2019). "In cervical cancer, IL-6 expression promotes tumour proliferation by inducing vascular epithelial growth factor (VEGF)-dependent angiogenesis in a STAT3 dependent manner and has also been suggested as a potential biomarker." (PMID 31226168, 2019).
cervical carcinoma (continued). "Upon STAT3 depletion we observed a marked reduction in the levels of IL-6 mRNA, IL-6 protein expression and secretion, indicating that STAT3 likely drives a mechanism to maintain enhanced IL-6 expression in cervical cancer cells." (PMID 31226168, 2019). "IL-6 has been proven to induce epithelial–mesenchymal transition in human cervical carcinoma cells via STAT3 activation." (PMID 31470515, 2019). "High levels of IL-6 have been detected in various types of human epithelial cancers and correlate with the proliferation or survival of cervical cancer cells." (PMID 31816985, 2019). "To corroborate these findings in primary tumours, we mined an available microarray database of normal cervical samples against cervical cancer samples and revealed a statistically significant increase in IL6 mRNA expression in the cervical cancer samples." (PMID 31226168, 2019). "Here, we show that STAT3 phosphorylation in HPV positive cervical cancer cells is mediated primarily via autocrine activation by the pro-inflammatory cytokine Interleukin 6 (IL-6)." (PMID 31226168, 2019). "As expected, our results demonstrated that IL-6-induced STAT3 activation was reduced in TMS-TMF-4f-treated cervical cancer cells." (PMID 31816985, 2019). "Several studies reported that constitutive and IL-6-induced STAT3 activation is common in cervical cancer cell lines and tissues." (PMID 31816985, 2019). "MiR-155-5p promotes cervical cancer progression by secreting proinflammatory cytokines, including IL-6 and IL-8." (PMID 31595161, 2019). "In cervical tumorigenesis, the activated IL-6 and STAT-3 induced senescence of fibroblasts in high-risk Human Papilloma Virus-infected cervical cancer." (PMID 29360827, 2018). "Upon treating with FSK, IL-6 was observed to be down regulated in a dose dependent manner, implying that FSK potentially down regulates IL-6 in cervical cancers." (PMID 30558287, 2018). "Reports on the functions of miR-1248 are limited, but one report indicated that miR-1248 over-expression in HeLa cells, a cervical cancer cell line, resulted in upregulation of inflammatory cytokines (IL-6 and IL-8) and other markers of inflammation." (PMID 29178897, 2017). "At the same time paracrine IL-6 can limit NF-κB-dependent anti-viral and anti-tumor immune responses in APCs, further highlighting IL-6 as an attractive target for adjuvant immunotherapy of cervical cancer." (PMID 28895886, 2017). "For instance, cervical carcinoma cells can induce the tolerogenic phenotype in macrophages through the secretion of IL-6 and PGE2." (PMID 29445756, 2017). "Strikingly, when the IL-6/STAT3-signaling pathway is activated in cervical cancer cells, they are more efficiently killed by chemotherapeutic drugs, such as cisplatin or etoposide." (PMID 28895886, 2017). "Earlier studies have shown that IL-6 concentrations increase with the development of clinical stages in patients with cervical cancer." (PMID 26289850, 2016). "Several studies have described a pleotrophic multifunction of IL-6, both in chronic inflammation and in some types of cancer, including cervical cancer." (PMID 26990868, 2016). "CUR and Nano-CUR were also able to suppress IL-6 and BaP-induced migration of cervical cancer cells." (PMID 26837852, 2016). "They place stress on the important role of proinflammatory cytokines, IL-6 included, in the progression of cervical cancer, particularly in early stages of development." (PMID 26289850, 2016). "IL-6 is a central proinflammatory cytokine involved in female genital infection and is abundant in the microenvironment of cervical cancer." (PMID 27690342, 2016). "All these results indicated that LYN promoted cervical cancer cells metastasis through activating IL-6/STAT3 pathway." (PMID 27690342, 2016). "Serum level of VEGF, CYFRA 21.1 and IL-6 before treatment in patients with early stage cervical cancer appears to be an important prognostic factor." (PMID 26289850, 2016).
cervical carcinoma (continued). "It is already known that the cancer-associated fibroblast senescence induced by high-risk -E6, activates IL-6/STAT3 signaling and remodel tumor microenvironment favoring the development of cervical cancer after the elongated latency of the disease." (PMID 26308848, 2015). "miR-21 is known to promote cell proliferation and initiate inflammation-associated carcinogenesis via nuclear factor kappa-light-chain-enhancer of activated B cells (NF-kB) and interleukin-6 (IL-6) signaling pathways in colon and cervical cancer cells." (PMID 26010154, 2015). "IL-6 has been frequently detected in the stromal region of cervical cancer tissues containing a large number of fibroblasts." (PMID 26010154, 2015). "Additional experiments showed that IL-6 exposure in cervical carcinoma cell lines induced IL-6R and STAT3 expression, promoted cell growth, and altered cell morphology." (PMID 25590298, 2015). "Treatment of cervical carcinoma cell lines with IL-6 resulted in down-regulation of E-cadherin and up-regulation of vimentin." (PMID 25590298, 2015). "Further, the analysis revealed VEGFA and IL-6 proteins as the distinctly high degree nodes in the disease network, which are known to manifest a major contribution in promoting cervical cancer." (PMID 26308848, 2015). "Activation of the STAT3 pathway is required for IL-6-induced EMT in the progression of human cervical carcinomas." (PMID 25638155, 2015). "Considering the clinical relevance of the STAT3 signaling pathway in cervical carcinoma we focused the remaining studies of this work on the effect of endothelial cell-secreted IL-6 in the biology of adenocarcinoma cells." (PMID 24533454, 2014). "In accordance with our observations, it has been reported that IL-6 is expressed by cervical carcinoma cells infected with HPV and, on the other hand, IL-13 expression was demonstrated in cell lines derived from Hodgkin disease and pancreatic cell lines." (PMID 25309919, 2014). "Expression levels of TGF-β, IFN-γ, IL-6, IL-10, IL-17 and IL-23 are elevated in cervical cancer patients and CIN patients." (PMID 23587428, 2013). "We found that levels of TGF-β, IL-6, IL-10, IL −17 and IL-23 in patients with cervical cancer and cervical CIN were significantly higher than those in the control group." (PMID 23587428, 2013). "Collectively, the expression levels of TGF-β, IFN-γ, IL-6, IL-10, IL-17 and IL-23 were up-regulated in cervical cancer patients." (PMID 23587428, 2013). "Expression and production of inflammatory cytokines, including IL-6, are elevated in carcinoma of the cervix, where they act as autocrine growth factors to regulate the inflammatory response via induction of the PTGS2-PGE2 signal transduction pathway." (PMID 22442729, 2012). "IL-6 is found in high concentrations in cervical cancer tissues and has been shown to up-regulate vascular endothelial growth factor (VEGF), and thus vascularization of neoplasias, in a dose-dependent manner." (PMID 19440442, 2009). "Our results are thus in agreement with previous studies that showed a correlation between the number of tumour associated macrophages and IL-6, IL-8 or MCP-1 levels in breast and cervical cancers." (PMID 17261184, 2007). "The IL-6/IL-1β-STAT3-CD274 axis-mediated immune escape during cervical cancer pathology may also exist during HPV infection, and curdione and borneol can block this process through modulating inflammatory factors." (PMID 39911394, 2025). "In cervical cancer HeLa cells cultured with fluoride concentrations of 1–50 mg/L for 48 h, there was a strong increase in IL-1β, IL-6, and TNFα levels in the supernatant at the lowest concentration (1 mg/L), followed by a significant decrease at higher concentrations." (PMID 40497976, 2025). "Additionally, IL-6 secreted by HPV-positive cervical cancer cells induces STAT3 activation in neighboring HPV-negative cervical cancer cells, thereby enhancing cancer cell proliferation." (PMID 41488475, 2025).
cervical carcinoma (continued). "IL-6 likely plays an important role in the tumor microenvironment of cervical cancer." (PMID 39207449, 2024). "Similarly, piperine selectively induces cellular senescence by releasing SASP and IL-6 in HeLa cervical cancer cells while suppressing premature senescent human diploid fibroblasts (S-HDFs), similar to normal cells." (PMID 39342176, 2024). "In this study, we found that IL-6 and IL-8 could promote the phosphorylation levels of Jak-2 and Stat3 proteins in cervical cancer cells." (PMID 39193386, 2024). "In addition, we also demonstrated that recombinant IL-6 and IL-8 proteins can promote the phosphorylation of Jak-2 and Stat3 in cervical cancer cell lines, and anlotinib can neutralize this promoting effect." (PMID 39193386, 2024). "To clarify the specific effects of IL-6, IL-8 on cervical cancer cell lines, we added human recombinant IL-6 and IL-8 proteins to anlotinib-treated CAF-CM and found that it restored the promotional effects on the proliferation and invasion of cervical cancer cell lines." (PMID 39193386, 2024). "Furthermore, they also demonstrated a positive correlation between Orai1 and IL-6 expression in human cervical cancer samples." (PMID 37759164, 2023). "Regardless of time (pre- or postoperative), a positive correlation was observed between plasma levels of IL-6 and IL-10 (P < 0.05), suggesting that these two cytokines may play a key role in immune regulation in cervical cancer." (PMID 36053326, 2023). "Furthermore, we also observed a positive correlation between Orai1 and IL-6 expression in human cervical cancer samples." (PMID 36310590, 2022). "Interestingly, exogenous IL-6 abrogated the effects of Orai1 silencing and restored the clonogenicity of cervical cancer cells." (PMID 36310590, 2022). "Taken together, Orai1 promotes the growth of cervical cancer cells by increasing IL-6 expression." (PMID 36310590, 2022). "Further, employing synthetic poly-methyl methacrylate adjuvant with a recombinant E7 DNA vaccine could increase the level of TNF-α and IL-6 in cervical cancer models." (PMID 35752792, 2022). "Furthermore, Orai1 expression was positively correlated with IL-6 expression in the cervical cancer tissues." (PMID 36310590, 2022). "Finally, Orai1 knockdown also repressed IL-6 secretion from the cancer cells, indicating that the oncogenic effects of Orai1 in cervical cancer is mediated via increased production of IL-6." (PMID 36310590, 2022). "Furthermore, IL-6 is also essential for the proliferation of HPV-positive cervical cancer cells via STAT3 activation." (PMID 36310590, 2022). "Taken together, inhibition of Orai1 decreased IL-6 expression in cervical cancer cells." (PMID 36310590, 2022). "In addition, very interestingly, one study found that autocrine and paracrine phosphorylation of STAT3 in HPV-positive cervical cancer cells are driven by activation of the IL-6 signaling axis, thus promoting the proliferation of cervical cancer cells." (PMID 35570248, 2022). "The pooled analysis showed that XRCC3 RS861539, TNF-α rs1800629, and IL-6 rs1800795 were associated with cervical carcinoma susceptibility, but not MTHFR rs1801133, IL-12B rs3212227 and TLR9 rs352140 polymorphisms." (PMID 34837895, 2021). "Furthermore, genotype GG of IL-6 rs1800795 was more frequent among control women than in the cervical cancer group (44% vs. 25.8%, <0.012)." (PMID 34684062, 2021). "Lactate produced by cervical cancer cells stimulates the secretion of interleukin-6 (IL-6) and IL-10 as well as upregulates HIF-1α expression and decreases p65 NF-κB activity in tumor-associated macrophages, contributing to a procancerous M2 macrophage phenotype." (PMID 34666780, 2021). "Our data show that IL-6 rs1800797 polymorphism is not a risk factor for cervical cancer in Lithuania." (PMID 34684062, 2021). "IL-6 rs1800797 genotypes and allele frequencies were not statistically different between women with cervical cancer and healthy controls." (PMID 34684062, 2021).
cervical carcinoma (continued). "RBM8A is known to be a component of the exon junction complex, which could regulate IL-6-induced STAT3 activation in human cervix carcinoma cell line." (PMID 32294703, 2020). "We further explored whether the regulation of poly(I:C) on IL‐6 expression in cervical cancer is related to its concentration and duration of action." (PMID 31943744, 2020). "Our results suggest that poly(I:C) can promote the expression of IL‐6 in cervical cancer cells, induce the local recruitment of macrophages and the secretion of pro‐inflammatory cytokines, while the resulting inflammatory environment increases the risk of tumour progression." (PMID 31943744, 2020). "Since poly(I:C) was found to promote the expression of IL‐6 in cervical cancer cells, we further explored whether IL‐6 is involved in the regulation of macrophage secretion by cervical cancer." (PMID 31943744, 2020). "This pathway may be one of the important factors for the formation of a special feature of local high IL‐6 expression in cervical cancer." (PMID 31943744, 2020). "Our patients’ data together with experimental evidence that chronic activation of STAT3 promotes tolerance toward cervical cancer antigens led us to investigate if IL-6 and G-CSF could have a role in tumor growth and modulation of tumor systemic effects." (PMID 33330068, 2020). "C1QBP promoter methylation could impede the host immune response by modifying interleukin 6 production and dendritic cell metabolism and maturation; activity important in cervical cancer cell progression." (PMID 32025240, 2020). "Furthermore, the contribution of IL-6 to STAT3 activation in cervical cancer remains poorly defined." (PMID 31226168, 2019). "Collectively, our work has demonstrated that the MUC1-EGFR-CREB/GRβ axis stimulates IL-6 expression to induce CSCs enrichment and importantly, this effect can be abrogated by erlotinib, uncovering a novel strategy to treat paclitaxel-resistant cervical cancer." (PMID 31772161, 2019). "Another study by the same research group demonstrated that cervical cancer cells increase IL-6 production, and the overexpression of this cytokine may promote cervical tumorigenesis by activating VEGF-mediated angiogenesis via a STAT3 pathway." (PMID 31470515, 2019). "Also, TMS-TMF-4f suppressed both constitutive and IL-6-inducible levels of phosphorylated STAT3 (p-STAT3) and associated proteins such as Mcl-1, cyclin D1, survivin, and c-Myc in both cervical cancer cells." (PMID 31816985, 2019). "We therefore tested whether AKT was involved in NFκB activation and IL-6 secretion in HPV positive cervical cancer cell lines." (PMID 31226168, 2019). "Interestingly, we observed that IL-6 protein expression in CIN3 and cervical cancer clearly stratifies into two sub-populations; IL-6 high and IL-6 low." (PMID 31226168, 2019). "Building on this, we analysed IL6 mRNA expression in all six cervical cancer cell lines." (PMID 31226168, 2019). "The HPV E6 oncoprotein aberrantly activates the signal transducer and activator of transcription 3 (STAT3) transcription factor and this is achieved by a virus-driven increase in the levels of the pro-inflammatory cytokine interleukin-6 (IL-6) in HPV positive cervical cancers cells." (PMID 31817106, 2019). "Therefore, it is possible that EGF can also regulate the production of IL-6 in HPV18 positive cervical cancer cells through induction of similar signaling pathways." (PMID 31470515, 2019). "Interestingly, IL-6 also enhances cervical cancer cell survival by upregulating the anti-apoptotic protein Mcl-1, which is mediated through the activation of the PI3K/Akt pathway." (PMID 31470515, 2019). "Furthermore, we demonstrate that NFκB is essential for IL-6 expression in HPV positive cervical cancer cells." (PMID 31226168, 2019).